AQP4 (aquaporin 4)
Diseases named in the same sentence as AQP4 in open-access papers (continued):
Sharing a sentence is not in itself a finding about the gene and the disease.
brain edema (continued). "The authors noted that the transient increase in neuroinflammation and relocalization of AQP4 water channels along the astrocytic processes away from the perivascular space could be a compensatory mechanism to reduce cerebral oedema and changes in intracerebral pressure." (PMID 34806002, 2021). "Notably, much experimental evidence demonstrates the role of AQP4 in the resolution of brain edema." (PMID 34483842, 2021). "Therefore, the timing of AQP-4 inhibition is important for therapy for brain edema in TBI." (PMID 34203960, 2021). "Moreover, AQP-4, an intrinsic pro-inflammatory factor, is only activated by the inflammatory factors in the brain tissue and promotes swelling in astrocytes, secretion of inflammatory cytokines, as well as the occurrence of cerebral edema." (PMID 33240266, 2020). "However, not only the character of AQP4 reactive changes allows us to speculate that vasogenic edema was involved in pathophysiology of brain edema after decompressive craniectomy in our model." (PMID 30333785, 2018). "Previous studies on cerebral edema found that reduced levels of AQP4 significantly improved the outcome, which suggests that maybe the α2Na+/K+-ATPase works independently of AQP4 in the area tested, or maybe the effect would be more evident in later stages after SCI, which awaits future testing." (PMID 28886701, 2017). "Thus, regarding the edema protection property, melatonin could change the transcriptional activity of edema related molecules, such as AQP-4 and TJPs, which is important for its improvement in brain edema." (PMID 28351378, 2017). "Based on this information we could possibly explain why most of the studies in TBI demonstrate an increase in AQP4 expression post-injury, and also why studies or treatments that result in AQP4 reduction/inhibition in these settings could possibly reduce brain edema." (PMID 28036023, 2016). "However, the involvement of AQP4 is considerably complicated in the pathogenesis of brain edema." (PMID 25941935, 2015). "Furthermore, AQP4 is also related to the incidence of cerebral edema." (PMID 26385393, 2015). "We wanted to know whether AQP4 plays a role in hypoglycemia-induced brain edema." (PMID 25264602, 2014). "Hence, it appears that AQP-4 channels, which play a key role in development of brain edema, may be modulated by V1a antagonism." (PMID 25403760, 2014). "The two consistent results show that AQP4 overexpression may elicit a negative effect on cerebral oedema caused by cerebral I/R." (PMID 24520266, 2014). "While the siRNA approach is unlikely to be utilized as a specific drug for preventing edema formation, research on AQP4 inhibition by siRNA in animals will be valuable for validating the hypothesis that inhibiting AQP4 activity is a potential therapeutic target for managing brain edema." (PMID 39944892, 2025). "Astrocyte aquaporin 4 (AQP4) polarization was also a proposed mechanism of action to stabilize BBB dysfunction and prevent cerebral edema." (PMID 41515925, 2025). "AQP4 inhibitors such as AER-270 and acetazolamide have demonstrated significant potential in reducing cerebral edema and improving outcomes in animal models of ABI." (PMID 39768394, 2024). "Aquaporin 4 (AQP4) is a water channel that allows bidirectional water diffusion across the astrocyte membrane and participates in the distinct phases of cerebral edema." (PMID 39043897, 2024). "Another compound with an appropriate affinity for AQP4 is the Aeromics/Simcere drug, AER-270, an investigational drug that was found to reduce cerebral edema." (PMID 38255997, 2024). "New AQP-4 partial antagonists, AER-270 and AER-271, have demonstrated beneficial results in brain edema models." (PMID 38003477, 2023). "A study by Nasution and colleagues showed that treatment with CAPE reduces AQP4 mRNA expression in the brain and AQP4 protein levels in the blood, suggesting this as a mechanism of action of CAPE in alleviating brain edema." (PMID 37240254, 2023).
brain edema (continued). "CGRP can reduce the overexpression of the aquaporin-4 (AQP-4) protein and its mRNA in the cerebral ischemic junction, and play a role in reducing cerebral edema." (PMID 37529236, 2023). "For example, progesterone treatment downregulates aquaporin-4 (AQP-4) in the lateral ventricles and surrounding tissues in the injured brain and significantly reduces the degree of cerebral edema after subarachnoid hemorrhage." (PMID 35305084, 2022). "Especially, aquaporin-4 (AQP4), a main water channel in the central nervous system, is known to have a key role in the formation of cerebral edema." (PMID 35474489, 2022). "Because miR-7-5p can inhibit the activity of the PI3K/AKT pathway, it can inhibit AQP4 expression by inhibiting the PI3K/AKT pathway and, consequently, brain edema." (PMID 33392188, 2020). "Positive effects of progesterone on brain damage were also demonstrated in neonatal rats with induced hypoxic ischemia; downregulation of AQP4 expression and MMP-9 in progesterone-treated animals had beneficial effect on alleviation of cerebral edema." (PMID 33297299, 2020). "Another research demonstrated that AQP4 played a beneficial role in facilitating reabsorption of fluid in vasogenic edema, including some models of TBI, cerebral edema and SCI, thus AQP4 reduced the degree of vasogenic edema during this period." (PMID 31258460, 2019). "Our previous work has verified a rat model of hypoglycemia-induced brain edema and has shown that the breakdown of the BBB after hypoglycemia can be attributed to the degradation of TJs and altered AQP4 expression." (PMID 29793504, 2018). "We next examined if levels of AQP4 was altered following SCI, in line with previous studies on cerebral edema." (PMID 28886701, 2017). "Recently, 2-(nicotinamide)-1,3,4-thiadiazole (TGN-020) was identified as a novel aquaporin 4 (AQP4) inhibitor and administration of TGF-020 reduced ischemic cerebral edema in mice." (PMID 25941935, 2015). "Accumulating evidence indicates that aquaporin 4 (AQP4), the most abundant water channel in the brain, also plays an essential role in the pathogenesis of cerebral edema." (PMID 24416250, 2014). "Aquaporin-4 (AQP4), as the most abundant water channel in the central nervous system (CNS), plays an important role in the formation and resolution of brain edema, but has opposite effects on different brain edema types." (PMID 23805198, 2013). "Therefore, a new function of AQP4 is probably related to its action on intracellular Ca2+ dynamics, as also suggested by altered spontaneous Ca2+ oscillations observed in ANSCs from AQP4−/− mice, and more recently, in astrocytic Ca2+ signaling events elicited by cerebral edema." (PMID 21552523, 2011). "Although it is unlikely that RNAi could be used as an efficient drug to rapidly block astrocytes swelling, AQP4 inhibition studies by RNAi in animals will be very useful to test the hypothesis that the inhibition of AQP4 activity is a potential target for the treatment of brain edema." (PMID 21119880, 2010). "AQP4 upregulation further increases brain water content, but MRI detection shows no worsening of brain edema, and neurological function scores improve." (PMID 39530196, 2025). "The correlation between AQP4 expression and cerebral edema was assessed by correlation analysis using SPSS software, which showed that the expression level of AQP-4 was positively correlated with the severity of cerebral edema." (PMID 40406486, 2025). "It was postulated that drugs that could inhibit the function of AQP4, such as AER-271, would potentially reduce the development of cerebral oedema." (PMID 40869387, 2025). "And the degree of cerebral edema in RIBI could be reduced by treatment with AER-271, which further confirms that AQP4 plays an important role in the cerebral edema link in RIBI." (PMID 40406486, 2025). "Prior research has indicated that AQP4 and HIF-1α may have a synergistic effect in the pathogenesis of cerebral edema." (PMID 39619615, 2024).
brain edema (continued). "This suggests that the slight elevation in AQP4 levels, induced by the anti-HMGB1 mAb in the present study, may facilitate the recovery phase of brain edema." (PMID 38892076, 2024). "Anti-HMGB1 treatment partially reversed the decrease in AQP4 levels, suggesting its potential role in mitigating brain edema, but did not significantly affect the reduction in PAR-1 levels." (PMID 38892076, 2024). "In addition, diacerein ameliorates hyperammonemia induced cerebral edema and maintains BBB integrity through modulation of TLR4/AQP4/MMP-9 axis." (PMID 39556255, 2024). "AQP4 KO mice exhibit a 25–60% decrease in glymphatic CSF tracer influx, and acute pharmacological blockade of AQP4 inhibits glymphatic transport using TGN-020 inhibitor, reducing severity of brain edema and lesion volume after ischemic injury." (PMID 36757363, 2023). "Mice without AQP4 show worse performance in neurologic scores and develop more severe brain edema by measuring brain-water content." (PMID 36248855, 2022). "Previous studies have shown that SFN could function to upregulate AQP4 expression levels in TBI animal models, resulting in relieving cerebral edema." (PMID 35991296, 2022). "Cerebral edema is no longer closely related to AQP4, which is more involved in the clearance of cerebral edema." (PMID 33613264, 2020). "Interestingly, aquaporin 4 (AQP4) and matrix metalloproteinase (MMP9) are integral components of the pathophysiology of brain edema and have become viable candidates for potential therapeutic targets for DHA." (PMID 32878052, 2020). "Previously, it has been shown that the mislocalization and not lower expression of the AQP4 protein is correlated with the delayed onset of imminent brain edema." (PMID 29445328, 2018). "AQPs, particularly AQP1 (found in vascular endothelium) and AQP4 (found in the brain and lung), may contribute to this permeability by facilitating water movement, which exacerbates tissue edema in organs like the lungs (ARDS) and brain (cerebral edema)." (PMID 39768394, 2024). "Other experimental therapies for cerebral edema require further study; examples include other SUR1 inhibitors (such as glimepiride and resveratrol), vascular-endothelial growth factor (VEGF) inhibitors, aquaporin-4 (AQP4) inhibitors, microRNAs, and other BBB protective agents." (PMID 37892779, 2023). "In cerebral I/R injury, NKCC1- and AQP4-mediated astrocytic swelling triggers JNK activation, which subsequently induces oxidative/nitrative stress and pro-inflammatory cytokine production, resulting in disruption of BBB integrity and exacerbation of cerebral edema." (PMID 33298024, 2020). "The accumulated results in our laboratory have demonstrated that up-regulated expression of MMP-9 and AQP4, and down-regulated expression of tight junction proteins, such as ZO-1 and occludin could be induced by 1,2-DCE poisoning during the course of brain edema." (PMID 29410610, 2018). "Cerebral edema seriously affects clinical outcome after ischemic stroke; we therefore aimed to investigate whether NMO-antibodies may exert the same functional effects as an AQP4-inhibitor in-vivo in acute ischemic stroke." (PMID 25986484, 2015). "In our study, we found that treadmill pre-training mitigated brain edema and BBB disruption, but down-regulated the expression of AQP4 after reperfusion, which indicated that the neuroprotective effects of exercise may be correlated with down-regulation of AQP4." (PMID 24416250, 2014). "The mechanism of HS down-regulation of AQP4 expression in cerebral edema is not yet known." (PMID 23036239, 2012). "However, they did not study the mechanism of HS down-regulation of AQP4 expression in cerebral edema." (PMID 23036239, 2012). "While the cannabinoid receptors and AQP4 expression are not directly related following TBI, recent findings indicate that post‐traumatic declines in plasma concentrations of the endocannabinoids 2‐AG and AEA are associated with an increase in cerebral edema and AQP4 expression." (PMID 39496572, 2024).
brain edema (continued). "In addition, we have shown that knockout of AQP4 or TRPV4 can cause expression changes of other proteins, specifically glutamate receptors and ion channels, and thus the effect on the development of cerebral edema is not solely due to the specific deletion of these two channels." (PMID 38818517, 2024).
myelitis (141 papers, 2009 to 2026). An inflammatory process affecting the spinal cord. "Patients who are AQP4-IgG seropositive face a 60% risk of clinical relapse within 1 year following an episode of myelitis, highlighting the prognostic significance of serostatus." (PMID 40933045, 2025). "Dividing our cohort into diagnostic subgroups allowed for clinically relevant comparisons between “double-seronegative” myelitis and patients meeting diagnostic criteria for AQP4-IgG seropositive NMOSD and MOGAD." (PMID 39442039, 2025). "In this retrospective study of carefully selected patients with myelitis associated with rheumatologic disease (unrelated to typical MS), we found that nearly half had AQP4-IgG seropositive NMOSD while a small but clinically significant proportion had MOGAD." (PMID 39442039, 2025). "Patients with AQP4-IgG positive who experience a myelitis episode have a 60% risk of another episode within 1 year." (PMID 38899058, 2024). "Tonic spasms and severe neuropathic pain associated with myelitis are less common compared to AQP4+NMOSD." (PMID 36419536, 2022). "The risk of severe motor disability is greater in subjects with AQP4+NMOSD presenting with myelitis than in those presenting with ON." (PMID 36419536, 2022). "Younger children tend to have longitudinally extensive myelitis, such as with MOG-antibody associated myelitis and idiopathic TM, so this characteristic of anti-AQP4 antibody-mediated NMOSD is less specific in the pediatric population." (PMID 31109018, 2019). "AQP4 + NMOSD is a primary cause of longitudinally extensive myelitis." (PMID 38473365, 2024). "Multivariate analysis showed that longitudinally extensive myelitis and AQP4-IgG are independent risk factors for the development of spinal movement disorders, while MOG-IgG and African American race were associated with a lower risk of developing these movement disorders." (PMID 38977461, 2024). "In this review we will summarize the current knowledge of the myelitis associated with the three most well-characterized demyelinating CNS disorders, namely MS, AQP4+NMOSD and MOGAD, describe their clinical and imaging features and discuss the short- and long-term outcomes." (PMID 36419536, 2022). "Our findings implicate that the complement-independent pathologies induced by AQP4–IgG may cause subtle abnormalities in motor function, and these pathologies may explain the mild and asymptomatic myelitis observed in some NMOSD patients." (PMID 29988553, 2018). "Therefore, we suggest that low-dose MMF can be used in clinical practice, especially in patients in South China with a high relapse risk, high serum AQP4-IgG titers and long segment myelitis, but patients must be closely monitored for adverse reactions." (PMID 30258442, 2018). "Moreover, 29.42 % of anti-AQP4 (+) ABS patients experience recurrent brainstem symptoms before attack of ON or myelitis, which suggested that anti-AQP4 antibody associated recurrent brainstem symptoms should be paid more attention." (PMID 27769253, 2016). "Furthermore, we detected M-23 AQP4-IgG in two patients with myelitis (CIS and SLE), who harbour the risk of later developing NMO and could benefit from an appropriate early treatment." (PMID 20463974, 2010). "The proportion with at least 1 relapse of myelitis was greater in the AQP4-IgG seropositive NMOSD group (12 of 20, 60%) compared with the “double-seronegative” group (3 of 17, 18%; p = 0.019)." (PMID 39442039, 2025). "When examining CSF white blood cell count collected within 30 days of myelitis onset, this was overall higher in “double-seronegative” patients compared with the AQP4-IgG seropositive NMOSD group (eTable 2; p = 0.34) but this was not statistically significant." (PMID 39442039, 2025). "Patient 3 experienced a recurrence of myelitis 7 months later, accompanied by elevated AQP4 antibody titers." (PMID 40777035, 2025). "Further research is needed to characterize myelitis etiology in patients who are seronegative for both AQP4-IgG and MOG-IgG." (PMID 39442039, 2025).